CD44 (CD44 molecule (IN blood group))
Diseases named in the same sentence as CD44 in open-access papers (continued):
Sharing a sentence is not in itself a finding about the gene and the disease.
cancer (continued). "Thus, a significant area of study is aims to further define the functional roles of the different CD44 isoforms in various types of cancers." (PMID 34944493, 2021). "Moreover, CD44 was also well known to be critical in stemness maintenance in various cancers, including breast cancer, liver cancer, pancreatic cancer and bladder cancer." (PMID 34959397, 2021). "Furthermore, we discovered that two other cancer stem cell-related genes, Cd44 and Itga6, were also significantly upregulated in the tumors." (PMID 33652981, 2021). "Furthermore, published cancer surface markers CD44 and CD59, as well as the insulin-like growth factor binding protein 2 (IGFBP2), were expressed in all analyzed CSCs." (PMID 33800955, 2021). "It is apparent that CD44 isoform switching mediated by alternative splicing of CD44 has an impact on epithelial-mesenchymal transition and similarly on metastatic behavior of cancer cells." (PMID 34257584, 2021). "In addition, the cancer cells of TNBC have self-renewal and regenerating characteristics, such as cancer stem cells, based on the expression of cell-surface markers CD44+CD24− and aldehyde dehydrogenase 1 (ALDH1)." (PMID 34500557, 2021). "CD44 is known for its role in cancer cell migration and proliferation." (PMID 34206049, 2021). "Besides analyzing the described Notch signaling pathway components, we investigated the two cancer stem cell markers CD44 and MSI." (PMID 33498866, 2021). "Furthermore, CPX exposure significantly decreased spheroid formation and cancer stem cell marker proteins (CD44 and SOX9), suggesting that CPX acts, at least in part, through effects on CSCs." (PMID 34059639, 2021). "Moreover, CD44 expression was upregulated in many cancer cells and recognized as a cancer stem cell marker." (PMID 34681583, 2021). "Also, gene expression of cancer stem cell-related surface markers CD44 and CD133 were found to be highly expressed in the sorted CD133+ cells at the basal level." (PMID 34071008, 2021). "Therefore, blockage of HA-binding to CD44 has been proposed as a potential therapeutic strategy for cancer." (PMID 33810348, 2021). "CD44 is expressed in many types of human cells including embryonic stem cells and cancer cells." (PMID 34599251, 2021). "The expression of CD44 has been used as a putative marker for cancer stem cells." (PMID 34884848, 2021). "Recently, it has been shown that CD44 is expressed in cancer cells and may be cleaved at the ectodomain by membrane type 1- matrix metalloproteinase (MT1-MMP), forming soluble CD44." (PMID 33681421, 2021). "CD44 is a transmembrane glycoprotein that behaves as a (co)receptor for hyaluronic acid, growth factors, and cytokines and is involved in the proliferation of cancer cells." (PMID 34946546, 2021). "CD44 expression correlates with unfavorable clinical outcomes in multiple types of cancer." (PMID 33810348, 2021). "Since xenograft mice models do not fully reflect the nature of the human body, one major reason could be that CD44 is indeed expressed by many healthy cells and its targeting might mediate toxicity in cancer patients." (PMID 34944493, 2021). "Furthermore, the cell surface adhesive molecule CD44 can potentially interact with Gal-9; their binding regulates leukocyte migration during allergic lung inflammation and cancer metastasis by inhibiting the CD44–hyaluronic acid (HA) interaction." (PMID 33804076, 2021). "A soluble form of CD44 exists and is also overexpressed in certain cancers." (PMID 34638469, 2021). "Hyaluronan-CD44 interactions have a substantial impact on stemness properties of cancer stem cells and drug resistance through promotion of the epithelial-to-mesenchymal transition program, epigenetic control, oxidative stress resistance, and secretion of exosomes/extracellular vesicles." (PMID 35111687, 2021). "Finally, cancer stem cell markers CD44, CD133, and NESTIN displayed a similar averaged RNA expression to 2D grown cells." (PMID 33356003, 2021).
cancer (continued). "Finally, cellular uptake experiments confirmed the CD44-mediated internalization of nanoparticles in cancer cells." (PMID 33652648, 2021). "We confirmed that CD44+ was acquired in the livers of mice with HCC, that it was predominantly expressed in macrophages, and that its expression was closely associated with expansion of CD4 T cells which characterise a cancer permissive environment." (PMID 34408183, 2021). "Silybin (150 μM) decreased HCT116 derived CD44+ cancer stem-like cells to ~48% after 48 hr." (PMID 34094034, 2021). "Interestingly, CD44-STn contributes to cancer tolerogenic immune responses and cell invasion, whereas MUC16-STn is expressed by subgroups of patients that do not respond to cisplatin-based therapeutics." (PMID 34108014, 2021). "Summary of CD44 interactomes and their effects on cancer progression." (PMID 34944493, 2021). "On the other hand, CD44 was altered both in patients vs healthy subjects and in cell models, suggesting that this could be a cancer-related marker of spreading and prompting a deeper investigation of this antigen in BC patient EVs." (PMID 34820420, 2021). "In addition, miR-34a was found to affect the expression of cancer stem cells (CSCs) overexpressing CD44, leading to tumorigenesis and recurrence, while inhibiting the proliferation, metastasis, and survival of CD44-positive CSCs." (PMID 34966746, 2021). "This review summarises current research regarding the different CD44 isoform structures and their roles and functions in supporting tumourigenesis and discusses CD44 expression regulation, CD44-signalling pathways and interactions involved in cancer development." (PMID 34944493, 2021). "The majority of prostate cells in BPH non-cancer specimens were CD44-/CD24+ and CD44-/CD24-." (PMID 34019593, 2021). "CD44 is overexpressed on cancer cells, which aids in cell migration and invasion." (PMID 33925129, 2021). "Moreover, soluble E-selectin in the serum was described to facilitate circulating CD44-expressing cancer cells and immune cells homing to tissues, thus contributing to tumor metastasis and growth." (PMID 33477563, 2021). "Emerging roles of CD44 have been demonstrated in CSCs and show that it may be a promising biomarker for different types of cancers." (PMID 34949193, 2021). "Despite the cancer cells captured by F7 or SP peptide were identified as CSCs that expressed CD44, single peptide binding cells (F7+ or SP+) and double peptides binding cells (F7+ /SP+) were considered as different subpopulations that exist at the different stages of cancer." (PMID 34789743, 2021). "The Bi2Se3 HNC-s-s-HA/GA could target CD44-overexpressing cancer cells, achieve GSH-sensitive GA release, and inhibit HSP90, and could hence accomplish more efficient low-temperature PTT under mild NIR laser irradiation." (PMID 34041494, 2021). "Moreover, expression of the cancer stem cell surface marker CD44+CD24-/low subpopulation, which is measured by flow cytometry and mammosphere forming efficiency, was also reduced after NUP37 downregulated." (PMID 34386417, 2021). "CD44(+) cells demonstrated cancer stem-like cell properties and created sphere colonies." (PMID 34336089, 2021). "Hyaluronan is primarily produced by fibroblasts present in the stroma and interacts with the cell surface receptor CD44 to regulate a cascade of pathways involved in cell proliferation, migration, and invasion, and thus plays an important role in cancer progression and metastasis." (PMID 34901028, 2021). "In addition, we investigated some cancer stem cell markers and we demonstrated an increase in Cd44, Nt5e and Aldh1a1." (PMID 34670568, 2021). "Therefore, in vivo biodistribution and imaging findings in human cancer-bearing mice that better predicts the results in human subjects will be benefited from the use of an Ab that cross-reacts with both murine and human CD44." (PMID 33594192, 2021).
cancer (continued). "Likewise, CD44 expression was diminished in gastrointestinal cancer cells forced to express miR-328, resulting in cancer cell growth inhibition and impaired resistance to chemotherapy and reactive oxygen species (ROS)." (PMID 34944493, 2021). "Notably, overexpression of the cancer-stem-cell-marker CD44 enhanced the stability of SLC7A11 by promoting the interaction between SLC7A11 and OTUB1; the depletion of CD44 partially abrogated this interaction." (PMID 33540700, 2021). "The decrease of Bmi‐1 expression and proportion of CD44+/CD24− subpopulation cells showed the loss of stemness and that TM‐induced ER stress might result in differentiation of cancer stem cells." (PMID 34320274, 2021). "In SPNs-treated PANC-1 cells, under-expression of miR-155, miR-21, and miR-222 in association with the decrease in CD markers CD24, CD44, and CD133 may indicate the importance of SPNs in inhibition of onco-miRs and stemness properties of PANC-1 cancer cells." (PMID 34094034, 2021). "Amongst the CD44 spliced variants, CD44v6 is highly expressed along with OPN in several cancers." (PMID 34944493, 2021). "In addition, CD44 is a molecule whose main ligand is hyaluronic acid and promotes migration and metastasis in different cancer types." (PMID 34136383, 2021). "It has been also shown that CD44 plays a crucial role in cancer progression." (PMID 34796172, 2021). "In agreement with previous studies, we showed that ERK–ZEB1 signaling promotes epithelial to mesenchymal transition in cancer cells, and treatment of CD44-overexpressing cells with ERK phosphorylation inhibitor PD98059 reversed ZEB1 and Claudin-1 expression levels." (PMID 34439211, 2021). "CD44 as a cancer stem cell (CSC) marker may be cleaved by MT1-MMP and plays an important role in migration of cancer cells." (PMID 33681421, 2021). "The analysis showed the amplification of CCND1/CDK4/PLK1/CD44 based on percentages of separate genes, with 7% for CCND1, 2.9% for CDK4, 1.7% for PLK1, and 1.8% for CD44 in multiple cancers, including the missense mutation amplifications, deep deletions, and alteration frequencies of these oncogenes." (PMID 34063946, 2021). "Similarly, when assessing these growth factor effects on the CD44+/CD24−/low cancer stem cell population, we found that BMP4 acted as a differentiation factor, able to decrease both basal and TGFβ-induced BCSC numbers." (PMID 33649296, 2021). "Interestingly, photoactivated TMA was also able to affect Wnt signalling and CD44 expression, both involved in cancer stem cell (CSC) growth and renewal." (PMID 33504020, 2021). "For example, HA could be specifically recognized by CD44, a receptor overexpressed on many cancer cells." (PMID 34336811, 2021). "However, genes associated with cell differentiation (EPCAM, CK8, CK18, and FOXA2), EMT (SNAI1, FOSL1, and ID1), and cancer stem cells (CD44, CD133, ETV1, MALAT1, NEAT1, and NESTIN) displayed a more varied response compared to 2D cells." (PMID 33356003, 2021). "The cancer stem cells were isolated by CD44+ selection using magnetic cell-sorting." (PMID 34205649, 2021). "Different investigations have shown that PD-L1 expression is not equal in all cancer cell groups, for example, in head and neck, lung, and breast cancer PD-L1 expression is mainly associated with CD44+ cells, a marker closely associated with GCSCs." (PMID 34503571, 2021). "Because the CD44 antigen used in the immunization was generated in the mouse, the plasmid expressed a glycosylated CD44 protein, but glycosylation was not necessarily like that of native CD44 proteins formed in human cancer cells." (PMID 33891595, 2021). "The CD44 isoforms not only play major roles in a host of cellular functions ranging from embryogenesis to the cell physiology of adults in a variety of tissues, but also in cancer tumorigenesis." (PMID 33891595, 2021).
cancer (continued). "Consistent with the gene expression in this study, and protein levels within a previous study, 3D cultured cells had upregulated protein levels of markers for cancer stemness (CD44) and pluripotency (POU5F1), and downregulated levels of markers for proliferation (CCNA2) and differentiation (ERS1)." (PMID 34869246, 2021). "The authors speculated that higher TEVs CD44 expression correlated with the more aggressive glioblastoma cell line, indicating their potential involvement in metastasis in this type of cancer." (PMID 33540535, 2021). "Since CD44 is a CSC regulator in many cancers and is a direct target of miR-34a, it implies that both c-Myc and CD44 could act as ceRNAs for miR-34a." (PMID 33763422, 2021). "It is worth noting that hsa‐circ‐001680 can increase the proportion of CRC stem cells and increase the expression of stem cell markers such as SOX2, CD44, and CD133 from mRNA and protein levels, in which cancer cells with surface markers CD44+/CD133+ can develop their stem cell properties." (PMID 34796685, 2021). "Generally, the HA/Cis NG could efficiently realize a CD44-targeted delivery for cancers such as cisplatin monotherapy and cisplatin-based combination therapy." (PMID 34336811, 2021). "Expression of cancer stem cell markers, including CD44, CD133, Oct3/4, and ALP activity, may be one reason the growth of our cell cultures was suppressed." (PMID 34115931, 2021). "CD44 was also identified as a direct molecular target of miR-520b, whereby miR-520b inhibited tumourigenesis of head and neck cancer through the regulation of cancer stemness conversion." (PMID 34944493, 2021). "Decreased CSC phenotypes were found by interfering with CD44 expression in these cancer types." (PMID 34959397, 2021). "However, the function of CD44 isoforms differs in various cancers and different outcomes CD44 isoforms." (PMID 34513617, 2021). "In addition, it was shown that soluble E-selectin (which sheds from the activated endothelium) contributes to CD44-expressing breast cancer cells migration and shear-resistant adhesion, facilitating leukocytes and cancer cells homing to tissues." (PMID 33477563, 2021). "Interestingly, a depletion of CD44 leads to metabolic pathway changes resulting in redox status modification and Trolox (anti-oxidant) led to the recovery of the cancer cell functions." (PMID 33780455, 2021). "Alternative splicing of CD44 is tissue specific and often deregulated in cancer cells." (PMID 34257584, 2021). "Our findings demonstrated that CD44 protein appeared to play important roles in cancer progression." (PMID 33780455, 2021). "CD44 is a well-known stem cell marker and is known to be activated in malignant tumors." (PMID 33540700, 2021). "Moreover, fluorescence‐activated cell sorting (FACS) analysis results showed that the populations of cells positive for the biomarkers of cancer stem cells, CD44, CD133, and ALDH, were significantly increased among cells overexpressing CUL4B." (PMID 34026424, 2021). "Moreover, CD44 is expressed in cancer stem cells that survive chemotherapy in models of glioblastoma, breast, pancreatic, colorectal, and prostate cancer." (PMID 33810348, 2021). "All these CD44+ cancer cells were resistant to HA-induced anti-migratory effects." (PMID 34770956, 2021). "This system efficiently identified characteristic CD9, CD44 and epithelial cell adhesion molecule (EpCAM) surface proteins, demonstrating that it could be used for cancer diagnosis and cell phenotype characterization." (PMID 34440265, 2021). "Clinical significance of various CD44 isoforms in certain cancer types." (PMID 34257584, 2021). "In addition, HA-modified nanoparticles exhibited targeted delivery to cancer cells that expressed high levels of CD44." (PMID 32982750, 2020). "PAA reduced Nanog, Sox2, Oct4, and CD44 gene transcripts of cancer cells." (PMID 33202749, 2020).
cancer (continued). "Attributable to the CD44 targeting effect of HA, the final NPs could be uptaken by CD44-overexpressed cancer cells for synergistic PDT/PTT." (PMID 32211603, 2020). "CD44 has also been studied as a therapeutic target in several cancers." (PMID 33000243, 2020). "miR-34a-5p could inhibit metastasis and cancer stem cells by directly repressing CD44 in prostate cancer." (PMID 31892992, 2020). "In addition, according to the results of Western blot experiments, MCF-7/SC were found to possess higher levels of cancer stem cell markers such as CD44, MRP1, and MDR1 and lower levels of CD24 compared with MCF-7 cells." (PMID 32503225, 2020). "Similarly, we showed that the alternative splicing of CD44 was closely related to the adaptive response and plasticity of cancer cells." (PMID 33024087, 2020). "The inhibition of CD44 expression showed therapeutic effects, such as the reduction of cell migration and invasion, suggesting that magnetic nanostructures have the potential for miRNA-based cancer therapy." (PMID 32792960, 2020). "Similarly, another study suggested that interactions among HA, CD44, and emmprin contribute to cancer cells with glycolytic phenotype and other malignant properties." (PMID 32825245, 2020). "CD44 is overexpressed in several cancers and is a molecular marker for stem cells." (PMID 32922663, 2020). "Additionally, in previous work from our group, CD44 was identified in GC cell lines as a potential secreted biomarker with immature O-glycans, which was validated in cancer patients′ sera." (PMID 31973075, 2020). "In parallel, following exposure to H. pylori, changes were evident in levels of mRNA expression of epithelial to mesenchymal transition (EMT)-encoding factors including snail, slug, vimentin, matrix metalloprotease, zinc finger E-box-binding homeobox, and the cancer stem cell marker CD44." (PMID 33233485, 2020). "Moreover, other collagen receptors such as integrins or CD44, that can also be found on stromal cells as well as cancer cells, have also been shown to be involved in invadosome formation." (PMID 32984031, 2020). "Thus, the CSC markers, CD44, CD44v6, CD44v8-10, and EpCAM have the potential to predict cancer recurrence including CCA." (PMID 32039729, 2020). "Soluble CD44, CD44v6, CD44v8-10 and EpCAM are promising factors for predicting cancer recurrence." (PMID 32039729, 2020). "Besides mAbs, recent development of anti-CD44 CARs has opened new opportunities for treatment of CD44-expressing cancers." (PMID 33081391, 2020). "CD44+/CD24-expressing cancer cells have a high capacity for invasive properties." (PMID 33202749, 2020). "However, CD44+ is also expressed by many non-cancer cells in tumors, such as immune cells and vascular endothelial cells, suggesting a need to combine CD44 with additional markers to differentiate between different populations residing in tumors." (PMID 35582216, 2020). "Moreover, together with epithelial cell adhesion molecule (EpCAM), CD133, CD90, CD24, and CD13, CD44 was also characterized as a cancer stem cell (CSC) marker." (PMID 31991677, 2020). "Furthermore, Western blotting was used to detect changes in EMT markers, kinase pathway proteins, and the CD44 cancer stemness marker in PKAP+ shCD34 cells compared to the shcontrol group." (PMID 32586050, 2020). "Besides overproduction, CD44 cross-linking is also believed to induce cancer cell adhesion and migration." (PMID 33292278, 2020). "Expression of different CD44 isoforms positively correlates with poor clinical outcome in various cancers, such as breast, colon, lung, bone, pancreatic, colorectal, bladder, gastric, and head and neck squamous cell carcinomas, as well as leukemias and lymphomas." (PMID 33335857, 2020). "CD44 overexpression or alternative splicing was described for many types of cancers." (PMID 32388640, 2020).